FOXP3 (forkhead box P3)
Diseases named in the same sentence as FOXP3 in open-access papers (continued):
Sharing a sentence is not in itself a finding about the gene and the disease.
glioblastoma (31 papers, 2010 to 2025). The most malignant astrocytic tumor (WHO grade IV). "In glioblastoma patients, a more aggressive clinical course has been associated with Foxp3+ T regulatory cells, which mediate immune tolerance and inhibit antitumor immune responses." (PMID 36311792, 2022). "Tumor-infiltrating lymphocytes (TILs) serve as representative markers for the predominant presence of CD8+ cytotoxic T lymphocytes (CTLs), CD3+ T cells, and CD4+/FoxP3+ regulatory T cells (Tregs) within the glioblastoma (GBM) tumor microenvironment (TME)." (PMID 38732975, 2024). "(ii) Resveratrol combined with radiotherapy decreases percentage of CD3+CD8+T and IFN-γ+CD8+T cells and increases percentage of (CD4+CD25+Foxp3)/CD4+T cells in glioblastoma tumor tissues." (PMID 36276282, 2022). "Lastly, GzB+ Foxp3+ cells were identified in human primary glioblastoma tissues suggesting a potential role of cyTreg in the tumor microenvironment (TME) not previously recognized." (PMID 35493508, 2022). "Of all the GBMs, we found that mesenchymal glioblastomas have higher expression of Foxp3 than proneural and classical tumors." (PMID 33429364, 2021). "Increased numbers of forkhead box P3 (FOXP3)+ Tregs were found in glioblastoma; however, their correlation with patient survival was modest." (PMID 33572835, 2021). "Our result provided a novel vision to study glioblastoma and we will verify the accuracy of the Foxp3-related IPS by our data in further research works." (PMID 33429364, 2021). "One study found a correlation between PD-L1 expression and a marker of regulatory T-cells, FoxP3, as well as between FoxP3 expression and patient survival in patients with glioblastoma." (PMID 30568917, 2018). "Further studies are required to investigate the molecular mechanisms responsible for FOXP3 down-regulation in glioblastomas." (PMID 23888189, 2012). "Additionally, our scRNA-seq dataset revealed FOXP3 expression in a small proportion of glioblastoma Tregs, and expression of ITGA1, ITGAE, and CXCR6 which are associated with a Trm signature." (PMID 35464424, 2022). "(2013) demonstrated that an EGFRvIII-specific bispecific T-cell engager (BiTE) could redirect human CD4+CD25+CD127dim/- Foxp3+ Treg and activate them in the presence of glioblastoma tumors expressing EGFRvIII." (PMID 35493508, 2022). "Here, we report that FOXP3 is expressed in normal brain but strongly down-regulated in glioblastoma (GB) and in corresponding GB stem-like cells growing in culture as neurospheres (GB-NS), as evaluated by real time-PCR and confirmed by immunohistochemistry on an independent set of GB." (PMID 23888189, 2012). "In summary, our study provided evidences that FOXP3 facilitates the progression of glioblastoma by inhibiting ferroptosis via the linc00857/miR-1290/GPX4 axis, highlighting FOXP3 as a potential therapeutic target for GBM." (PMID 38561331, 2024). "In this study, our objective was to investigate the impact of FOXP3 on glioblastoma multiforme (GBM) cells." (PMID 38561331, 2024). "This study analyzed the effect of Foxsp3 on the immune microenvironment and constructed a Foxp3-related immune prognostic signature (IPS)for predicting prognosis in glioblastoma multiforme (GBM)." (PMID 33429364, 2021). "Cancer cells and TAMs induce CD4+FoxP3- type I regulatory T cells (Tr1) cells in glioblastoma (GBM) patients." (PMID 32595638, 2020). "One of the hallmark features of glioblastoma multiforme (GBM), the most common adult primary brain tumor with a very dismal prognosis, is the accumulation of CD4+CD25+Foxp3+ regulatory T cells (Tregs)." (PMID 23720663, 2013). "In glioblastoma multiforme (GBM) cells, FOXP3, belonging to the forkhead box (FOX) family, was found to upregulate the transcription of GPX4, but it also attenuated the degradation of GPX4 mRNA through the linc00857/miR-1290 axis, thereby suppressing ferroptosis and promoting proliferation." (PMID 39125992, 2024).
glioblastoma (continued). "Tumor infiltrating lymphocyte (TILs) obtained from glioblastoma patient’s tumor specimens (n = 4) were evaluated for the presence of CD4+, CD8+, T reg (CD25+ FOXP3), and microglia (CD11b + CD45), through flow cytometry." (PMID 36299858, 2022). "Yet, a recent study demonstrates that post infusion of CAR T cells, tumor specimens in glioblastoma patients have markedly increased expression of many immunosuppressive molecules, particularly IDO1 and FoxP3, and in some cases, IL-10, PD-L1, and/or TGF-β." (PMID 29685162, 2018). "In clinical studies of HNSCC, cervical cancer and glioblastoma multiforme, combination chemo-radiotherapy (CRT) depleted CD4+ and CD8+ Teff in the peripheral blood and TDLN of patients, while highly suppressive FoxP3+ Tregs were unaffected or expanded." (PMID 27509527, 2016). "However, existing studies regarding clinical significance of Foxp3+ tumor-infiltrating lymphocytes (TILs) in glioblastoma (GBM) remained discrepant." (PMID 24276989, 2014). "Several mechanisms such as hypoxia, immunosuppressive cytokine production, reduced T-cell proliferation, and effector response, activation of FoxP3 + regulatory T (Treg) cells and myeloid-derived suppressor cells (MDSC) mediate the immunosuppression in glioblastoma." (PMID 36299858, 2022). "Similarly, to assess the correlation between the expression of c-Met and FasL on GSCs with peripheral circulating immune cells, PBMCs of the same glioblastoma patients and healthy controls were evaluated for CD4+, CD8+, and T reg (CD25 + FOXP3) through flow cytometry." (PMID 36299858, 2022). "Indeed, immune cells isolated from peripheral blood of patients with glioblastoma exhibit more CD4+/CD25+/FOXP3+ Treg cells relative to those of patients without glioblastoma." (PMID 33396284, 2020). "We also conducted bioinformatics analysis in human tumor samples submitted to The Cancer Genome Atlas (TCGA) database, and we found that higher FoxP3+ Tregs correlated with lower survival in kidney renal clear cell carcinoma (KIRC) and glioblastoma multiforme (GBM)." (PMID 39773913, 2025).
squamous cell carcinoma (31 papers, 2009 to 2025). A carcinoma arising from squamous epithelial cells. "The YTHDF1 mRNA expression was also significantly negatively associated with CD4, CD8, and FOXP3 mRNA expression in squamous cell carcinoma." (PMID 36479088, 2022). "VISTA is expressed on tumour-infiltrating lymphocytes (TILs), myeloid-derived suppressor cells and regulatory T cells (MDSCs), regulatory T cells (CD4+CD25+Foxp3+Treg), dendritic cells (DCs), tumour associated macrophages (TAMs/MФ) and neoplastic squamous carcinoma cells." (PMID 36980527, 2023). "In patients with squamous cell carcinoma, PD-1 and IL-10R are co-localized whereas in patients with adenocarcinoma, an accumulation of IL-10R with Foxp3+ lymphocytes was found." (PMID 39325190, 2024). "We examined the TIL and tertiary lymphoid structure (TLS) density in the invading front and inner tumor stroma, and the lymphocyte subpopulation (CD8, CD4, FOXP3) density in 60 squamous cell carcinomas of the lip." (PMID 36900270, 2023). "The higher number (n > 29) of FOXP3+ cells was noted in 94.1% (32/34) with squamous carcinoma, while a lower number of FOXP3+ cells was observed in 79.1% (155/196) with squamous carcinoma." (PMID 31842422, 2019). "Intraepithelial tumor infiltrating lymphocytes: CD8+, CD4+, FOXP3+, CD56+, tumor associated macrophages: CD68+, and GZB+ cells were calculated in 85 vulvar squamous cell carcinomas with previously defined p16Ink4a and high-risk HPV-status." (PMID 28515351, 2017). "Squamous carcinoma and adenocarcinoma show increased Foxp3 expressions than large cell tumors (54.7% vs. 50.8% vs. 22.2%, p=0.018)." (PMID 27602763, 2016). "In the study of HPV+ tonsillar squamous cell carcinoma, FOXP3 is a favorable prognostic factor." (PMID 35719936, 2022). "The CD8+TIL density in the tumor area was significantly higher in the adenocarcinomas, and the Foxp3+TIL density in the stromal area was significantly higher in the squamous cell carcinomas, (CD8+TIL density in the tumor: P = .0018; Foxp3+TIL density in the stroma: P < .0001)." (PMID 32400056, 2020). "Similarly, a low CD8/FOXP3 ratio was correlated with worse disease-free survival in tonsillar squamous cell carcinoma." (PMID 30153850, 2018). "Regulatory T cells (Tregs) expressing the marker forkhead box p3 (Foxp3), recognized for their immunosuppressive properties, play a pivotal role in impeding anti-tumor immune responses, thereby facilitating the progression of AK to squamous cell carcinoma (SCC)." (PMID 38539468, 2024). "We found a significant association between PD-L1 expression and smoking intensity, histological type of squamous cell carcinoma, and the infiltration of the immune cells: CD4+ T cells, Foxp3+CD4+ T cells, CD8+ T cells, and M2 macrophages, in the tumour microenvironment." (PMID 38541208, 2024). "In contrast, PDPN expression, a demonstrated CSC marker in squamous carcinoma cells, while showing similar relationships with different TILs subtypes such as SOX2 and NANOG, was only significantly correlated with stromal and tumoral FOXP3+ cells." (PMID 34201050, 2021). "In general, the stroma of squamous cell carcinoma was characterized by a high content of CD68+ macrophages (p = 0.0343) and FOXP3+ regulatory T-cells (p = 0.0014), which indicates the distinctive properties of the microenvironment of this histological type of tumor." (PMID 32933105, 2020). "Similarly, smoking is also associated with squamous cell carcinoma (SCC) of the oral cavity, and increased Foxp3+ cells have been observed in SCC compared to non-cancerous epithelial tissues." (PMID 19330036, 2009).
allergic rhinitis (29 papers, 2009 to 2025). Inflammation of the nasal mucous membranes caused by an IgE-mediated response to external allergens. "The unusual associations of heterozygote of FoxP3 rs3761548 (AC genotype) have been reported in allergic rhinitis and Graves’ disease." (PMID 28298239, 2017). "Decreased PPG-stimulated IL-10 production, as well as decreased LPA-stimulated and PPG-stimulated FOXP3 expression, in cord blood were further identified as risk factors for a positive allergic status in children and allergic rhinitis (respectively)." (PMID 27646403, 2016). "To date, polymorphisms in the FOXP3 gene have been associated with a variety of immune-related diseases, such as allergic rhinitis, idiopathic infertility and endometriosis-related infertility." (PMID 23759077, 2013). "It has been confirmed that genetic polymorphisms in FOXP3 are related to the development of autoimmune diseases, such as allergic rhinitis, idiopathic infertility and endometriosis-related infertility." (PMID 23759077, 2013). "Additionally, the transcriptional level of FOXP3, which is closely related to Treg differentiation, was upregulated in the AR group, indicating that additional investigations are required to elucidate Treg-associated mechanisms in allergic rhinitis." (PMID 41376644, 2025). "Recent studies have suggested a potential relationship between Foxp3 expression dynamics and allergic rhinitis." (PMID 40430867, 2025). "These strengths enabled a more direct demonstration and analysis of the effects of intranasal injection of Foxp3 NPs on allergic rhinitis in the mouse model." (PMID 40430867, 2025). "Although increased Foxp3 expression in allergic rhinitis upon allergen exposure suggests the establishment of a counterregulatory mechanism, it is still insufficient to control the whole allergic inflammation." (PMID 38106504, 2023). "A more recent study has shown that Foxp3 expression in the nasal fluid of allergic rhinitis patients is lower than in healthy individuals outside of pollen season and increases during pollen season." (PMID 38106504, 2023). "A significant decrease in miR-146a expression in children with allergic rhinitis and its positive correlation with FoxP3 expression has been reported." (PMID 30808949, 2019). "A recent study showed that LGG in addition to vitamin D supplementation increased the number of CD4+CD25+FoxP3+ Treg in children with allergic rhinitis." (PMID 27525046, 2016). "Several studies have shown that both allergic rhinitis patients and healthy, non-allergic individuals have allergen-specific Th2 cells, but FOXP3+Tregs and/or Tr1 cells in allergic rhinitis patients are either dysfunctional or reduced in numbers." (PMID 26866695, 2016). "In our previous study, we observed that the expression of Foxp3 mRNA was downregulated in allergic rhinitis and nasal polyps, and treatment with a topical steroid enhanced the expression of Foxp3 mRNA and increased Treg accumulation in nasal polyps." (PMID 19250527, 2009). "Given the widespread use of steroid nasal sprays in patients with allergic rhinitis, it is anticipated that Foxp3 NPs nasal sprays may one day become a common therapeutic option for these patients." (PMID 40430867, 2025). "In contrast, Foxp3 expression in asthmatic patients remains low upon allergen exposure, suggesting a worsened impaired function of T regulatory cells compared with that of allergic rhinitis patients." (PMID 38106504, 2023). "This lipid has been shown to induce the expression of FOXP3 by inhibiting histone deacetylation, resulting in systemic anti-inflammatory properties via the expansion of Tregs, which was reported to be significantly lower in patients with allergic rhinitis." (PMID 38090578, 2023).
allergic rhinitis (continued). "It has been reported that the relative abundance of CD4+CD25+Foxp3+ Tregs was decreased significantly in a Guinea pig model of allergic rhinitis and that increasing the percentage of CD4+CD25+Foxp3+ Tregs restrains allergic reactions through an increase in IL-10 production." (PMID 34147127, 2021). "Moreover, we observed fewer Helios+Foxp3+, Helios+CD25+, and Helios+Foxp3+CD25+ Tregs in the nasal mucosa in the allergic rhinitis model." (PMID 31974056, 2021). "Therefore, manipulation of FOXP3+Tregs or Tr1 cells is currently explored as targets of novel treatment strategies to cure allergic rhinitis." (PMID 26866695, 2016). "Adoptive transfer CD4+CD25+FoxP3+Tregs of VD3 supplementation groups promoted Th1 and suppressed Th2 responses in the offspring during allergic rhinitis." (PMID 33954205, 2021). "Our findings indicated that low dose VD3 supply in pregnant mice's diet suppressed Th2 and Th17 responses in allergic rhinitis by elevating the Th1 subtype and the proportion of CD4+CD25+FoxP3+Tregs in offspring." (PMID 33954205, 2021). "Employing this knowledge, this study aimed to evaluate alteration in the expression of the genes FOXP3, TGF-β, IL-17, IFN-γ, IL-10, and IL-4 following ARIT protocol in Iranian patients with allergic rhinitis." (PMID 31807241, 2019). "On the contrary, another study has demonstrated that nasal secretions of patients with allergic rhinitis had significantly lower FOXP3 mRNA compared to nonallergic controls." (PMID 22164170, 2011). "To further characterize whether γδ T cells could influence Treg in allergic rhinitis (AR) and SIT, we investigated the expression pattern of Treg’s Foxp3 gene and γδ T cell receptor (TCR) Vγ subfamily genes in peripheral blood mononuclear cells (PBMCs) of AR patients before and after SIT." (PMID 24460842, 2014).
atopic dermatitis (29 papers, 2009 to 2025). "In conclusion, we have demonstrated that topical treatment of GCSE ameliorated the progression of experimental atopic dermatitis by reducing serum IgE and AD-associated pathogenic cytokines levels while increasing Foxp3 level." (PMID 24499290, 2013). "By contrast, atopic dermatitis-sensitive Pglyrp-deficient mice (Pglyrp3−/−, Pglyrp4−/− and Pglyrp2−/−Pglyrp3−/− mice) all had lower expression of FoxP3 mRNA in the affected ears compared to WT mice." (PMID 21949809, 2011). "Another recent cohort study highlighted a possible mechanism underlying the association between the level of vitamin D during pregnancy and the risk for atopic dermatitis through the downregulation of FOXP3 gene expression in the cord blood and decreased placental FOXP3 protein expression." (PMID 39247110, 2024). "Flow cytometry determined the proportion of CD4+RORγt+ Th17 cells and CD4+FoxP3+ Treg cells in cervical lymph nodes, as these cells play key roles in the pathogenesis of atopic dermatitis, particularly in the chronic phase." (PMID 38541664, 2024). "As contrast, CD4+FoxP3+ Treg cells were decreased in atopic dermatitis mice, and magnolol restoration of this decrease was found." (PMID 38541664, 2024). "Remarkably, it has been demonstrated in a mouse model of atopic dermatitis that administration of the ω-3 fatty acid docosahexaenoic acid upregulates the generation of TGF-β-dependent CD4+ Foxp3+ Tregs." (PMID 27175277, 2016). "Pglyrp3−/− mice in the atopic dermatitis model also had significantly lower numbers of CD4+FoxP3+ Treg cells in the affected skin compared to WT mice measured by flow cytometry." (PMID 21949809, 2011). "It has been shown that Ag85B DNA immunization can prevent and treat atopic dermatitis through the induction of Foxp3+ T regulatory (Treg) cells." (PMID 19531238, 2009). "In atopic dermatitis models, oral Rh1 administration at 20 mg/kg promoted a regulatory phenotype by increasing forkhead box P3 (Foxp3) mRNA expression in draining lymph nodes while decreasing IL-4 expression, suggesting dual action through both Th2 suppression and regulatory T cell enhancement." (PMID 41155644, 2025). "The protective effect of GCSE in experimental AD is mediated by inhibition of IgE production, by reduction in the levels of pathogenic cytokines and by induction of Foxp3, all of which are suggesting the beneficial effect of GCSE on modulating atopic dermatitis." (PMID 24499290, 2013). "In addition, ingestion of FFO markedly reduced IL-13 and IFN-γ levels and increased the expression of specific Treg cells markers (TGF-β and Foxp3) compared with NFO group in DNCB-stimulated atopic dermatitis mice model." (PMID 22873180, 2012). "Indeed, in the lesional skin of MF, the ratio of Foxp3 on CD25+ cells is higher than in eczematous dermatitis, suggesting that the ratio of Tregs among CD25+ cells might be higher in MF than in healthy controls." (PMID 37275413, 2023). "Atopic dermatitis increased the expression levels of T-bet and GATA-3 but decreased the expression of Foxp3 in BALB/c mouse, in an SOCS1-dependent manner." (PMID 30459600, 2018). "Because WT mice were able to limit skin inflammation in the atopic dermatitis model more effectively than Pglyrp3−/− and Pglyrp4−/− mice, we then tested whether this difference is due to impaired generation or function of regulatory T cells (CD4+FoxP3+ Treg) in Pglyrp-deficient mice." (PMID 21949809, 2011). "A DNCB-induced increase in CD4+RORγt+ Th17 cell fraction was reversed by DEX administration in the atopic dermatitis model but not a decrease in CD4+FoxP3+ Treg cell fraction." (PMID 38541664, 2024). "Atopic dermatitis increased the expression levels of T-bet and GATA-3 [transcription factors of T-helper 1 (Th1) and T-helper 2 (Th2) cells, respectively] but decreased the expression of Foxp3, a transcription factor of regulatory T (Treg) cells, in an SOCS1-dependent manner." (PMID 30459600, 2018).